RN7SL828P (RNA, 7SL, cytoplasmic 828, pseudogene)
Gene: Miscellaneous RNA gene on chromosome 11 (118,067,237 to 118,067,539, forward strand). Ensembl gene ENSG00000272075.
Homologues: Orthologues: chimpanzee Metazoa_SRP (98% identical), macaque Metazoa_SRP (92% identical), dog Metazoa_SRP (59% identical). Paralogues in human: RN7SL1 (85% identical), RN7SL2 (84% identical), RN7SL3 (84% identical), RN7SL126P (82% identical), RN7SL664P (82% identical), Metazoa_SRP (81% identical), RN7SL627P (81% identical), RN7SL113P (81% identical), RN7SL444P (81% identical), RN7SL679P (81% identical), RN7SL336P (80% identical), RN7SL620P (80% identical), and 701 more.